CD68 (CD68 molecule)
Diseases named in the same sentence as CD68 in open-access papers (continued):
Sharing a sentence is not in itself a finding about the gene and the disease.
tumor (continued). "The second type of area that frequently showed a high amount of PD-L1+ cells was located within tumor regions comprising neoplastic cells in close proximity to remaining acinus tissue associated with high abundance of CD3+ and CD68+ immune cells and low proportion of myofibroblasts (α-SMA)." (PMID 30899426, 2019). "The number of CD68+ macrophages in tumor tissues was positively correlated with TNM stage." (PMID 31601783, 2019). "This might indicate that there is a mixture of macrophage subtypes in the tumour, where some of those recognised by the pan-macrophage marker CD68 may have tumour-suppressive activities." (PMID 30808992, 2019). "Importantly, tumor-infiltrating CD68+ M and tumor expression of CD47 correlated with clinico-pathological features of PDAC patients in our study." (PMID 31771616, 2019). "Since stromal ST2 showed inverse correlation with stage and amount of desmoplasia, we evaluated other clinical factors involved in CRC prognosis, such as LN metastasis, tumor budding (TB) and macrophage markers (general marker CD68, M2-marker CD163, and M1-marker iNOS), analyzed by IHC." (PMID 31281317, 2019). "Flow cytometric analyses also revealed that the percentage of CD68+ rat macrophages within the tumour-infiltrating CD45+ leukocyte population was higher in the rat MOv18 IgE-treated cohort compared to the rat MOv18 IgG2b-treated or the vehicle alone-treated cohorts." (PMID 31544825, 2019). "Our immunohistochemical study revealed much more pronounced staining of the macrophage marker CD68 in lamina propria of tumor tissue from Tg-tRXRα mice than that from control mice treated with AOM/DSS, indicating an increased infiltration of inflammatory cells in Tg-tRXRα mice." (PMID 30931933, 2019). "In the present study, we performed a comprehensive comparison between HHLA2 and PD-L1 in terms of the expression pattern, clinical relevance and their associations with tumor infiltrating CD3+, CD8+, CD4 + Foxp3+, CD68+, CD163+ and CD20+ immune cells in a ICC cohort after curative resection." (PMID 30885276, 2019). "A study of primary testicular lymphoma found that the number of PD-L1+ CD68+ macrophages was positively correlated with the number of PD-1+ T cells in the tumor, and that patients with high levels of PD-L1+ CD68+ macrophages or PD-1+ T cell infiltration showed favorable survival." (PMID 31781673, 2019). "However, CD68+ TAMs accumulation was only slightly (but significantly) increased in 4T1 tumours from 300 mg/kg day metformin‐treated mice, while effects of 100 and 200 mg/kg day metformin were not significant." (PMID 29726618, 2018). "Moreover, analysis of Iba1 and CD68 immune-reactivity within the tumor mass reveals a different activation state of GAMs in cxcr6ko mice, indicating an effect of CXCR6 signaling on GAMs activation." (PMID 30542347, 2018). "Thus, we determined the percentage of TAMs (CD68+ cells) and MDSCs (Gr-1+/CD11b+ cells) in tumor sections by immunohistochemistry." (PMID 29755647, 2018). "Moreover, the presence of CD68+ TAMs in the tumor invasive front has been demonstrated to correlate with reduced tumor recurrence and to serve and an independent prognostic factor for survival." (PMID 30249019, 2018). "We also assessed the prognostic value of CD68+ macrophage numbers in the stromal and intra-epithelial compartments of these patients, compared to other classical risk factors such as tobacco and alcohol consumption, HPV status and tumor stage." (PMID 29541395, 2018). "The tumor cells expressed CD68 and CD163, and lysozyme and fascin, when tested." (PMID 30084011, 2018). "Tumour sections collected 5 days following IR showed a dense infiltrate of CD68+ macrophages." (PMID 30442705, 2018). "Thus, tumor mass and healthy colon sections were stained using a single hybrid protocol which combines immunohistochemistry for CD68 and fluorescence staining for polyP." (PMID 29543850, 2018).
tumor (continued). "Overall, density of tumor-associated macrophages (TAMs; CD68+) was higher in NCT tumors than in non-NCT tumors, and density of memory/regulatory cells (CD45RO + FOXP3+) was lower in the NCT group than in the non-NCT group." (PMID 29871672, 2018). "Since they were mononuclear cells present in tumor microenvironment, mainly in stroma, we conducted immunofluorescence staining using markers for mast cells (mast cell tryptase), macrophages (CD68), plasma cells (CD38), T- and B- lymphocytes (CD3, CD20 and CD79a) and neutrophils (NE)." (PMID 29543850, 2018). "Moreover, another antagonist of CXCR4, the peptide R, decreases the tumor mass of GB-xenotransplanted cells and reduces the CD11/CD68-positive cells in peritumoral zone of the tumor." (PMID 30123112, 2018). "In a primary neuroblastoma without MYC-N amplification, CD1d-expressing CD68+ tumor-associated macrophages (TAMs) stimulate tumor growth through production of IL-6, and a high TAM gene signature is associated with poor prognosis." (PMID 30158927, 2018). "Indeed, we found a significant correlation between CD68+ macrophage number and tumor stage, with the density of CD68+ macrophages being higher in advanced stages (III and IV) in both intra-tumoral and stromal compartments." (PMID 29541395, 2018). "Indeed, we observed a significantly higher density of CD68+ macrophages in carcinoma compared to dysplasia (high-grade and low-grade) and to tumor-free peri-tumoral epithelia." (PMID 29541395, 2018). "However, we noticed a significant correlation between CD68+ macrophages and tumor stage (p = 0.004), showing a higher number of these cells in the stromal compartment of advanced-stage tumors (III and IV), such as in intra-tumoral regions." (PMID 29541395, 2018). "We found that LinTT1-FAM-PS colocalized with CD68 (>50% of colocalization), and showed partial colocalization with CD11b and CD206 (9% and 21% of colocalization, respectively) in tumors, confirming the targeting of tumor-associated macrophages." (PMID 29721153, 2018). "Moreover, when evaluating the stromal compartment, CD68+ macrophage density was significantly different depending on the observed tumor location (Kruskal–Wallis test, p < 0.05)." (PMID 29541395, 2018). "To further dissect the relationship between activated Wnt/β-catenin signaling and M2 macrophages in HCC patients, we determined the expression of CD68 (a pan macrophage marker), β-catenin and M2-related markers MR or Arg1 in 25 frozen tumor sections by immunofluorescence staining." (PMID 30022048, 2018). "BRAF_V600E cases had CD68+ TAM more diffusely intermingled with tumor cells." (PMID 29763623, 2018). "CD68+ comprised between 25 and 94% of pixels within the MC&M mask inside the tumor." (PMID 30619287, 2018). "In addition to improving overall metabolic health, metformin also decreased the number of aromatase-positive, CD68-positive macrophages within the tumor microenvironment, suggesting a new role for metformin in targeting immune cells." (PMID 29898754, 2018). "Furthermore, MT overexpression was found to be related to the presence of tumor-infiltrating CD68+ macrophages (p = 0.003)." (PMID 30139373, 2018). "Interestingly, although containing lower numbers of CD68+ cells compared to metastatic PyMT IkkβΔmye mice, lungs from tumor free IkkβΔmye animals showed a clear trend towards increased presence of CD68+ cells as well." (PMID 29682184, 2018). "USP24 strongly co-localized with CD68, implying that USP24 might be highly expressed in tumor-associated M2 macrophages and might be involved in tumor-associated macrophage-mediated cancer progression." (PMID 30266897, 2018). "Additionally, the amount of stromal CD68+ monocytes/macrophages correlated proportionally with the intensity of tumor PD-L1 labeling." (PMID 29190964, 2017). "In addition, low or non-p65 expressive CD68+ myeloid cells were found mostly away from the invasive and hyper vascular tumor compartments." (PMID 29062041, 2017).
tumor (continued). "In addition, the statistically significant enhancement of survival in combination treatment of recurrent tumor is possibly driven by recruitment of CD68+/pSTAT1+ macrophages and inhibition of angiogenesis." (PMID 28076333, 2017). "Additionally, a high Gal3/CD68 ratio correlated significantly (p < 0.05) with higher grading (G3) in tumor resection specimens." (PMID 29284429, 2017). "Interestingly, microscopic findings showed co‐infiltration of CD4+ and CD8+ lymphocytes in the tumor area in 27 of 36 cases, and CD68+ cells and FoxP3+ cells were diffusely infiltrated in the tumors." (PMID 28602029, 2017). "This suggests that CD68+ cells start to be recruited within the tumor." (PMID 29069812, 2017). "However, in the late post-irradiation tumors, we can detect the presence of CD68+ cells outside the tumor core (white arrows)." (PMID 29069812, 2017). "Furthermore, enhanced tumor growth and spreading are observed in CD68-DcR3 Tg mice, and the enhanced tumor growth is abolished by arginase inhibitor and histone deacetylase inhibitor sodium valproate." (PMID 28629361, 2017). "In summary, for HPV+ patients, PD-L1 expression does not correlate with clinical outcome but in the HPV ̄ tumour group, higher PD-L1 expression by CD68 cells is associated with a relatively better survival." (PMID 28122336, 2017). "These cells were immunoreactive to the common leukocyte IHC marker CD45 and the T-cell marker CD3, while negative for the macrophage marker CD68 and were considered tumor-associated lymphocytes (TILs)." (PMID 28152514, 2017). "However, there was a tendency towards better survival in patients with higher CD56 (p = 0.057) or CD68 (p = 0.061) densities in the center of the tumour." (PMID 29269742, 2017). "A high Gal3/CD68 ratio correlated with higher grading (G3) in oscc tumor resection specimens." (PMID 29284429, 2017). "PD‐L1 expression correlated with tumor infiltration by CD68+ and FoxP3+ cells." (PMID 28602029, 2017). "The tumor cells showed positive of CD68, S100, Vimentin and Ki-67 index 80%." (PMID 28386111, 2017). "The tumor cells expressed CD68, S100, CKpan and Ki-67 index 30%." (PMID 28386111, 2017). "We screened the expression and distribution of a panel of immune markers in ESCC primary tumor samples firstly, and found that the distribution of CD68 and interleukin 13 (IL-13) could distinguish between good and poor prognosis." (PMID 26771842, 2016). "Survival analyses assessed by Kaplan-Meier plots and log-rank tests disclosed that densities of both CD68 and IL-13 in tumor stroma were significantly positively correlated to the overall survival time and disease-free survival time of patients after operation (p < 0.0001)." (PMID 26771842, 2016). "Similarly in our study Gas6 expression in human tumor samples was mainly found in a subpopulation of CD68+ macrophages." (PMID 27486820, 2016). "Survival analyses assessed by Kaplan-Meier plots and log-rank tests demonstrated that densities of CD68 and interleukin 13 (IL-13) in tumor stroma were positively correlated with the overall survival of ESCC patients after operation (p < 0.01 for CD68, p < 0.001 for IL-13)." (PMID 26771842, 2016). "Analysis of potential biomarkers showed reduction of CD14+ monocytes in peripheral blood suggesting a PD effect of RG7356; one of the proposed modes of action is to trigger direct antitumor effects by activating CD68+ macrophages via Fc/FcgR interaction to phagocytose CD44-positive tumor cells." (PMID 27507056, 2016). "Further, a model based on tumor stroma densities of CD68 and IL-13 was constructed and it could significantly classify patients with poor or good prognosis." (PMID 26771842, 2016). "The tumor islet and stromal CD68+ TAM densities were reported in 4 and 5 articles, respectively." (PMID 27144518, 2016).
tumor (continued). "Histological examinations of dissected brain and tumour tissues were performed in all of the LPS-induced neuroinflammation rats and U87-MG-bearing mice used for the microPET scans to investigate microglial activation by CD68 staining." (PMID 26853260, 2016). "We previously reported that CD68+ macrophages accumulate in the benign parts of tumor-bearing prostate lobes (the TINT), that depletion of these cells inhibited tumor growth, and that HO-1 (presumably a tumor-stimulating factor) was markedly upregulated in rat TINT." (PMID 27280718, 2016). "Moreover, the patients with high infiltrating density of CD68+ macrophages in the tumor nest had a significantly worse OS than those with low infiltration (median OS: 1.40 vs. 3.10 years, P = 0.0332)." (PMID 27736796, 2016). "We studied the prognostic role of the number of tumor‐infiltrating CD68+ cells and of the plasma levels of TARC (thymus and activation‐regulated chemokine) in the context of interim PET in 102 patients with classical HL treated with Adriamycin, Bleomycin, Vinblastine, Dacarbazine (ABVD)." (PMID 26758564, 2016). "In addition to cytomorphological analysis, gene expression of tumor associated genes (Cytokeratin-18, Cytokeratin-19, Cytokeratin-20, Cytokeratin-7, EPCAM, MUC1, HER2, EGFR) and of leukocyte markers (e.g. CD45, CD68) was tested in enriched CTC fractions." (PMID 25862542, 2016). "Compared with the non-NED group, the tumor-associated macrophages (TAMs, stained by CD68) count in the NED group increased." (PMID 27034164, 2016). "The opposite polarization of CD68+ TAMs in the tumor islet and stroma may also interpret the different effects of these cells on patient survival." (PMID 27144518, 2016). "Meanwhile, the tumor stroma was also infiltrated by CD68-positive macrophages." (PMID 26769084, 2016). "In our current study CD68 staining captures both pro-inflammatory M1 and pro-tumor M2 macrophages." (PMID 27456063, 2016). "Mice lacking a functional gene for complement C5 had smaller primary tumors, which were less invasive and lacked the CD68+ macrophages that have previously been associated with metastasis in this type of tumor." (PMID 27105526, 2016). "Indeed, we found that, when compared to HGSOC, LGSOC patients showed a lower density of tumor-infiltrating CD68+ macrophage along with an attenuated M2-skewed (CD163+) phenotype." (PMID 27462782, 2016). "Finally, the percentage of CD68+ macrophages in the invasive margin was higher in well-differentiated tumor versus poorly differentiated tumors (70% vs. 23.5%, respectively)." (PMID 27689405, 2016). "S100A9 was detected in the CD68+ macrophages of tumor stroma." (PMID 26315114, 2015). "Quantification of all CICs in the tumor samples examined revealed that tumor cell-mediated engulfment (CD68−) constituted the majority of the structures identified (93%), only a small portion of them were mediated by macrophages (CD68+)." (PMID 26109430, 2015). "They noted that the clinical stage combined with the tumor CD68/CD3 ratio could be a potential tool for prognostication." (PMID 26197470, 2015). "Moreover, CD56 and CD68 positive cells play role in local immune response in patientswith HCC33, so the expressions of CD56 and CD68 wasinvestigated by tumor tissue IHC." (PMID 25928327, 2015). "When co-expressed, CD68 and HLA-DR indicate macrophages M1 known to suppress tumor development." (PMID 26305673, 2015). "Accordingly, the tumor shows variable immunoreactivity for myogenic markers and CD68." (PMID 25889780, 2015). "CD68 staining highlighted the presence of histiocytes in the tumor." (PMID 26474555, 2015). "We do not have data that can elucidate the subtype of the CD68 positive tumour associated macrophages at the invasive front in our own study." (PMID 26292086, 2015). "Moreover,the primary tumors with liver metastasis were markedly and extensively infiltrated by CD68-positive macrophages located in the central tumor stroma and at the invasive front of lesions." (PMID 26068788, 2015).
tumor (continued). "Macrophage infiltration in tumor tissue from patients was examined via CD68 immunostaining." (PMID 25596747, 2015). "In this work, we employed immunofluorescent method to stain a panel of human tumor samples simultaneously with antibodies against E-cadherin for Epithelium, CD68 for Macrophage and CD45 for Leukocytes, which we termed as “EML method” based on the cells detected." (PMID 26109430, 2015). "The importance of the CD163/CD68 and M1/M2 ratio is found in several other tumor types." (PMID 25192022, 2014). "The tumor cells in GCTs are strongly immunoreactive to S100 and CD68." (PMID 25364429, 2014). "The tumor spindle cells were positive for vimentin, CD68, CD45, and Ki-67 (labeling = 18%)." (PMID 25379319, 2014). "The expressions of CD68 and CD163 were significantly associated with lymph node status, and SOX2 was significantly correlated with pathological grade and lymph node status, whereas ALDH1 was correlated with tumor stage." (PMID 24883329, 2014). "Moreover, when only low numbers of CD68+ macrophages were localized in close proximity to tumor cells (H3), these macrophages rarely expressed HLA-DR (K3)." (PMID 24797069, 2014). "The tumor cells were strongly and diffusely positive for vimentin and CD68." (PMID 24959221, 2014). "CD68-positive macrophages characterized by their elongated, well-spread morphology as well as round shaped phagocytes were detected at the tumor – liver border both from the side of the tumor body and the liver and within the portal vein areas." (PMID 24905750, 2014). "The analysis of CD105+ MVD, Try+ McMD and CD68+ MphMD, depending on the tumor stage using a Student’s t-test, revealed that the values of CD105+ MVD for all stages and of Try+ McMD for stages IA and III, were lower intratumorally compared with the advancing edge." (PMID 24137338, 2013). "In summary, CD68-positive macrophages in the tumor microenvironment may be a factor in the elevation of sIL-2R in FL and may play a role in extranodal DLBCL." (PMID 24236041, 2013). "We have previously shown that a majority of the TAMs in the primary tumor core are double positive for the CD68 and F4/80 markers, and the TAMs in the invading tumor front are both CD68 and F4/80 double-positive as well as F4/80-positive and CD68-negative TAMs." (PMID 23940516, 2013). "However, the average density of CD163+ cells was 22.83-fold and 4.11-fold higher in tumor and peritumoral liver tissue, respectively, compared with that of CD68+ cells." (PMID 23555776, 2013). "In addition, the presence of ARG2-expressing stromal cells was closely correlated with higher tumor-infiltrating CD68+ macrophages and CD66b+ neutrophils, and lower tumor-infiltrating CD4+ T cells and CD8+ T cells." (PMID 23424623, 2013). "Furthermore, we analyzed the M1/M2 ratios based on TAMs staining with CD68+ HLA-DR+ or CD68+ CD163+ in two consecutive tumor sections from each patient." (PMID 24324582, 2013). "Detailed analysis of the intratumoral and the peripheral tumor areas revealed a significant increase in the CD68+-macrophage population in the tumor margin concomitant with increasing viral spreading and a significant loss of the intratumoral CD68+-macrophage population." (PMID 23441176, 2013). "A tumor marker profile showed tumor cell reactivity for CD68, calponin and focally for CD10." (PMID 23628229, 2013). "Given their lysosomal content, the tumor cells may exhibit immunoreactivity for macrophage markers such as CD68, as observed in the present study as well." (PMID 24376672, 2013). "Hence, we decided to stain sections of the primary tumor and of all five metastases of patient A as well as sections of the primary tumor obtained from patient B, with antibodies against CD68, a macrophage-specific antigen, and CD15, to detect neutrophils." (PMID 22448124, 2012).